INS (insulin)
Diseases named in the same sentence as INS in open-access papers (continued):
Sharing a sentence is not in itself a finding about the gene and the disease.
Insulin resistance (continued). "It seems that weight loss via decreased incidence of insulin resistance and insulin resistance remission, even with consumption of an insulinogenic diet, decreases circulating insulin levels by increasing the clearance rate." (PMID 36585722, 2022). "T2D is caused by the establishment of insulin resistance, where at normal plasma insulin levels, target tissues are unable to mount an integrated glucose-lowering response to insulin." (PMID 36499659, 2022). "The inefficient glucose uptake in conditions of insulin resistance causes hyperglycemia, which further stimulates insulin secretion to compensate the insulin insensitivity." (PMID 36465655, 2022). "Increased insulin resistance caused by PDA will subsequently result in a higher dose of insulin use, leading to increased exogenous hyperinsulinemia." (PMID 35252207, 2022). "Insulin resistance is commonly triggered either by insufficiency of insulin secretion or a high protein level, both of which can cause it." (PMID 36060389, 2022). "Obese individuals often have impaired insulin sensitivity, which causes pancreatic beta-cells to promote insulin production, leading to hyperinsulinemia and insulin resistance (IR)." (PMID 35162142, 2022). "PCOS is strongly associated with insulin resistance – around 75% of women diagnosed with PCOS also have impaired insulin sensitivity." (PMID 36457554, 2022). "Hyperglycemia, insulin resistance and high insulin requirements in T2D cause compensatory hyperinsulinemia and expansion of beta cells which gradually leads to a loss of beta cell mass." (PMID 36246880, 2022). "It is a metabolic disorder associated with chronic hyperglycemia due to insulin resistance and deteriorated β-cell function and consequently decreased insulin secretion." (PMID 35083338, 2022). "It is important to note that insulin resistance observed in cancer is different to what is observed in type-2 diabetes, being characterized by normal fasting glucose level associated with any insulin level (Dev, Bruera and Dalal, 2018)." (PMID 36158184, 2022). "A study of an Iranian population revealed that rs2970847 SNV downregulates insulin signaling pathways and is associated with insulin resistance." (PMID 36587194, 2022). "Primary aldosternism, another disease caused by excessive secretion of mineralocorticoids, is associated with insulin resistance and hyperglycaemia and hypokalaemia and inhibits insulin secretion." (PMID 35937831, 2022). "DM is a chronic inflammatory disease in which a deficiency in insulin secretion or action results in insulin resistance and, consequently, hyperglycemia." (PMID 35739932, 2022). "It is associated with insulin resistance (IR), the need for more insulin to achieve physiologic effects, i.e., peripheral glucose uptake and suppression of hepatic glucose production (HGP)." (PMID 36518108, 2022). "In the present study, FEO inhalation caused a decrease in insulin as well as insulin resistance levels." (PMID 35215391, 2022). "Lower serum levels of adiponectin and ghrelin have been associated with insulin resistance, poor insulin sensitivity, and the genesis of obesity and type 2 diabetes." (PMID 36305681, 2022). "As previously shown, the loss of CEACAM1 by >50% lowers hepatic insulin clearance to contribute to chronic hyperinsulinemia and its downregulatory effect on insulin receptor levels to sustain hepatic insulin resistance." (PMID 36009446, 2022). "The drastic downregulation of the claudin-5a gene observed in our study suggests that the gene was inhibited by insulin resistance, implying the second post-insulin immersion that caused further BBB disintegration." (PMID 35955446, 2022). "Insulin resistance promotes the increase of free fatty acids, with associated alterations on the insulin signaling pathway and the decrease in translocation of GLUT-4." (PMID 36233611, 2022).
Insulin resistance (continued). "Administration of gal-3 in vivo can also cause glucose intolerance and insulin resistance in mice, and gal-3 knockout mice have higher insulin sensitivity and glucose tolerance." (PMID 36230963, 2022). "A cohort study showed that weight gain in the first three months of life was associated with more fat, central adiposity, lower insulin sensitivity, and higher insulin resistance in early adulthood, including in SGA children with catch-up growth." (PMID 36714657, 2022). "Our findings of an association between MDS and insulin sensitivity are consistent with studies using less robust measures to quantify insulin resistance." (PMID 36297122, 2022). "The insulin signaling (IS) pathway is of paramount importance, considering all other cellular pathways linked to insulin resistance." (PMID 36479211, 2022). "Unexpectedly, however, GPX1-deficient mice were protected from HFD-induced liver insulin resistance and inflammation and maintained hepatic insulin sensitivity." (PMID 35740032, 2022). "Serum c-peptide can indirectly reflect the concentration of insulin, and abnormally increased insulin content together with insulin resistance is an independent risk factor contributing to the development of CSVD." (PMID 35169393, 2022). "Mice receiving Gal3 injections developed insulin resistance and glucose intolerance, but obese mice receiving Gal3 treatment had enhanced insulin sensitivity due to pharmacological or gene loss." (PMID 36405706, 2022). "In contrast, higher WHRadjBMI was equally strongly associated with insulin resistance phenotypes (elevated fasting insulin, low HDL cholesterol and raised triglycerides) compared to BMI in women although more weakly in men." (PMID 36558416, 2022). "The association between total GLP-1 levels, insulin resistance, and insulin sensitivity, and GLP-1 predictors were also analyzed." (PMID 36157456, 2022). "Glucocorticoids are associated with insulin resistance and antagonize (counteract) insulin-mediated uptake and utilization of glucose in adipose tissue and muscles." (PMID 35897752, 2022). "Corticosteroids can promote PTDM through various mechanisms, inducing or worsening insulin resistance, increasing hepatic gluconeogenesis, reducing insulin secretion and, in the longer term, causing weight gain and visceral fat redistribution." (PMID 36359224, 2022). "The high hepatic influx of fructose has a lipogenic effect, which impairs the insulin signaling pathway causing insulin resistance and dyslipidemia." (PMID 36035416, 2022). "In a large cohort of 77 patients, the insulin response was almost doubled upon glucose loading, which was associated with a significant increase of the insulin resistance index." (PMID 35894287, 2022). "For decades, FFA has been an important risk factor for insulin resistance, defective insulin secretion, glucose intolerance, and T2DM." (PMID 36339436, 2022). "Metabolic syndrome is believed to affect cardiovascular risk mainly through insulin resistance, defined as a decreased responsiveness to insulin." (PMID 35242041, 2022). "Decreased glucose uptake as seen in skeletal muscles of type 2 diabetes following insulin resistance is thought to be caused by a defect in insulin signalling or abnormal deposition of transporter in the membrane compartments." (PMID 36418342, 2022). "The abnormal expression of inflammatory factors and oxygen free radicals can cause macrophage infiltration in adipose tissue, block the insulin signaling pathway, lead to insulin resistance, and induce type II diabetes." (PMID 36176638, 2022). "Confirmation in humans was derived from the insulin resistance already observed in pregnant women in association with increased erythrocyte GPx1 activity and also from enhanced insulin sensitivity in patients with global genetic selenoproteins deficiency." (PMID 35204134, 2022). "Low GLU concentration obstructs INS secretion, lipid mobilization, and ketogenesis and predisposes to insulin resistance." (PMID 36355173, 2022).
Insulin resistance (continued). "Conversely, elevated levels of insulin resistance markers within the brain are associated with worse performance on cognitive tests of episodic and working memory, suggesting a role for insulin signaling in neuronal functions." (PMID 35628384, 2022). "Obesity is also related to insulin resistance, which causes the insulin-mediated inhibition of DNL to disappear." (PMID 36077235, 2022). "FGF21 and adiponectin are described as insulin sensitizers, and a high leptin level is associated with insulin resistance." (PMID 35327418, 2022). "In clinical practice, insulin resistance refers to a state in which a given insulin concentration is associated with a subnormal glucose response to endogenous and/or exogenous insulin." (PMID 35889752, 2022). "Murine cry1 and cry2 gene deletions are associated with disruptions in the circadian rhythmicity of insulin and glucagon secretion, which in turn are associated with insulin resistance, hypertension and impaired glucose tolerance and dyslipidemia." (PMID 36034454, 2022). "In this regard, since obesity is frequently associated with a state of insulin resistance, it has been observed that impaired insulin signaling plays an important role in modulating the body's immune response." (PMID 35721580, 2022). "Serum DPP-4 levels are significantly higher in obese than normal-weight subjects, and are positively associated with fasting blood glucose and insulin concentrations as well as with insulin resistance index (HOMA-IR)." (PMID 35628332, 2022). "Both impaired insulin secretion and increased insulin resistance have been implicated as underlying causes of glucose homeostasis in PPGL patients." (PMID 36569401, 2022). "Insulin resistance (IR) is a state of metabolic disorder in which the responsiveness of insulin-dependent tissues is reduced, leading to an elevated risk of diabetes mellitus and cardiovascular diseases (CVD)." (PMID 35879737, 2022). "The two major underlying mechanisms in the pathogenesis of T2DM are insulin resistance and deficient insulin secretion." (PMID 36246870, 2022). "T2DM affects the majority of diabetic individuals, causing insulin resistance and insulin secretion problems." (PMID 35268815, 2022). "Insulin resistance, a common pathological feature of obesity, occurs when organs are insensitive to insulin stimulation, leading to high blood sugar levels, thus causing diabetes." (PMID 35757707, 2022). "Another article presented evidence that TCF7L2 rs290487, rs6585194, and rs7094463 polymorphisms were associated with insulin resistance and insulin secretion in women with GDM." (PMID 36339414, 2022). "It has been reported that muscle attenuation in post-stroke hemiparetic patients is negatively associated with fasting plasma insulin levels, which means that the increased intramuscular fat causes insulin resistance and relates to the risk of type 2 diabetes." (PMID 35277045, 2022). "An estimated 1.26 billion adults worldwide have insulin resistance (IR), a complex pathophysiological state connected to an imbalance between insulin and glucose metabolism, which is strongly associated with the development of cardio-metabolic disease." (PMID 35013420, 2022). "Taken together, these results indicate that high insulin levels and/or the associated insulin resistance, can contribute to the development of cellular senescence." (PMID 36072934, 2022). "The inflammatory genes and macrophage-specific genes are upregulated in white adipose tissue of patients with obesity, followed by an increase in circulating insulin levels, and they have been proposed to be linked to insulin resistance." (PMID 35712257, 2022). "From a mechanistic standpoint, chronic low-grade inflammation, central insulin resistance, and decreased CNS insulin levels have all been implicated in the increased risk for neurodegeneration in patients with obesity." (PMID 35334932, 2022).
Insulin resistance (continued). "Distinct metabolites, consisting of amino acids, lipids, sugars and energy substrates are associated with glucose/insulin metabolism and diet and can predict future incidence of insulin resistance." (PMID 36145067, 2022). "Obesity-induced inflammation suppresses the insulin-signaling pathway, making the human body less responsive to insulin and increasing the risk of insulin resistance." (PMID 36015301, 2022). "Zhang and colleagues model is a spontaneous type 2 model of insulin resistance while our model is more consistent with insulin-deficient type 1 diabetes in ApoE−/− mice." (PMID 35048962, 2022). "An increase in oxidative stress can cause insulin resistance, impaired insulin secretion, and late diabetic complication." (PMID 35845257, 2022). "One study showed that mRNA expression levels of TNF-α in adipose tissue in obese individuals are strongly implicated in the pathogenesis of insulin resistance through impairment of insulin signaling in hepatocytes and adipose tissue." (PMID 35457158, 2022). "CIDEC expression is low in patients with insulin resistance and obesity, and weight loss surgery improves insulin sensitivity while increasing CIDEC expression." (PMID 35963433, 2022). "The intervention was superior to conventional education in terms of weight loss, fat reduction, total cholesterol reduction, fasting insulin reduction, and amelioration of insulin resistance." (PMID 35655279, 2022). "The risk of T2DM increases with age which is due to the deficiency of insulin secretion which develops with age, and growing insulin resistance caused by a change in body composition." (PMID 36289697, 2022). "Using rat models in which hypertension is associated with insulin resistance and like other conditions associated with insulin resistance, abnormalities in insulin-related pathways have been identified at different steps." (PMID 36289636, 2022). "Obesity is generally associated with insulin resistance in liver and muscle and increased risk of developing type 2 diabetes, however there is a population of obese people that remain insulin sensitive." (PMID 36394259, 2022). "In both experimental and epidemiological research studies, vitamin D insufficiency has been linked to lower insulin release, insulin resistance, and type 2 diabetes." (PMID 36407246, 2022). "High homocysteine levels are linked with T2D via insulin resistance as homocysteine was found to have adverse effects on β-cell glucose metabolism and cell viability, thereby impairing insulin secretory activity." (PMID 35627115, 2022). "Several studies have shown that abnormal islet vascularization is associated with obesity and insulin resistance, resulting in inflammation, impaired insulin release, and β cell death." (PMID 36470872, 2022). "Insulin sensitizers bind allosterically to InsR and sensitize insulin action to alleviate insulin resistance and minimize the hypoglycemia risk." (PMID 35502441, 2022). "STAT3 (Signal Transducer And Activator Of Transcription 3) activation has been informed to be implicated in the progression of diabetic insulin resistance by regulating set genes involved in glycolipid metabolism and insulin sensitivity." (PMID 35956419, 2022). "Cigarette smoking is associated with greater insulin concentration, hyperinsulinemia, insulin resistance, and MetS." (PMID 36585722, 2022). "Interleukin-1 (IL-1), interleukin-6 (IL-6), and tumor necrosis factor-α (TNF-α) are inflammatory cytokines that cause insulin resistance and also suppress insulin release, an effect that is concentration-dependent." (PMID 35959169, 2022). "In principle, obesity is known to cause insulin resistance and secondary insulin secretion abnormalities that lead to the development of type 2 diabetes (T2D)." (PMID 36589801, 2022). "In a meta-analysis that included three different ethnic groups, rs28919926 and rs146125471 showed associations with acute insulin resistance, and rs7579 with the insulin sensitivity index." (PMID 35883754, 2022).
Insulin resistance (continued). "Compelling evidence highlights the central role of β-cell failure (i.e., loss of glucose-regulated insulin secretion) in the transition from insulin resistance to sustained hyperglycemia and the development of Type 2 diabetes (T2D)." (PMID 35204835, 2022). "The effects of metformin in women with PCOS have been explained by the reduction of the insulin resistance-caused hyperinsulinemia due to increased insulin sensitivity and this is the foundation on which the other “insulin-sensitizing” drugs rest." (PMID 34983571, 2022). "Insulin resistance causes impairment of glucose metabolism leading to a compensatory increase in insulin production and hyperinsulinemia." (PMID 36368970, 2022). "Using insulin requirements during pregnancy as a surrogate marker for insulin resistance, our group has previously demonstrated that increased parity is associated with higher insulin requirements in T1D women, persisting after adjusting for maternal size." (PMID 36554709, 2022). "It probably increases the susceptibility of adipose tissue to insulin and, therefore, a reduced omentin level can lead to insulin resistance." (PMID 35276837, 2022). "Bone-derived hormones correlate with insulin secretion, insulin resistance, and glucose metabolism and are implicated in the development and outcomes of DM and DKD." (PMID 35966090, 2022). "Considering the role of insulin signaling in the brain, it is possible to establish that a pathological condition induced by insulin resistance can be associated with cognitive and metabolic alterations." (PMID 35741464, 2022). "We herein focus on the role of elevated plasma NEFA in insulin clearance, mainly in the liver, and how this is linked mechanistically to insulin resistance." (PMID 36009446, 2022). "Studies in Chinese Han population have shown that PPARD rs2016520 variant (also named +294T > C or -87T > C) is associated with blood glucose, insulin level and insulin resistance, and is a key factor affecting the development of metabolic syndrome and T2DM." (PMID 36051387, 2022). "Major causes of insulin resistance in T1D include insufficient endogenous insulin secretion and the toxic impact of chronic hyperglycemia." (PMID 35928900, 2022). "HBP activation has been linked to impaired insulin signaling: adipocytes treated with GlcN become insulin resistant and rats infused with GlcN also exhibit insulin resistance, similarly to GlcN‐treated mice." (PMID 36124412, 2022). "The direct contributions of insulin itself in causing or sustaining insulin resistance have received little sustained attention." (PMID 35897752, 2022). "Significant improvement in insulin resistance biomarkers, measured through fasting insulin, area-under-the-curve insulin, and Homeostatic Model Assessment for Insulin Resistance (HOMA-IR) index can be achieved with just ≥5% weight loss." (PMID 35276833, 2022). "For example, O-GlcNAcylation of protein-tyrosine phosphatase 1B regulates its phosphatase activity and affects insulin signaling, thus causing insulin resistance." (PMID 36295790, 2022). "For instance, Collinsella has been positively associated with insulin level and Homeostatic Model Assessment for Insulin Resistance (HOMA-IR) and negatively associated with insulin sensitivity." (PMID 35025980, 2022). "Systemic insulin resistance also causes chronic activation of local insulin signaling and energy disturbances in cardiac tissues, resulting in the development and deterioration of HF." (PMID 35941584, 2022). "Increased free fatty acids cause peripheral insulin resistance, as well as hampers the secretion of insulin by beta cells of the pancreas, resulting in elevated blood glucose levels." (PMID 36743935, 2022). "Obesity is closely correlated with impaired insulin signaling and is a major cause of the development of insulin resistance." (PMID 35548566, 2022).